CD4 (CD4 molecule)
Diseases named in the same sentence as CD4 in open-access papers (continued):
Sharing a sentence is not in itself a finding about the gene and the disease.
astrocytoma (13 papers, 2008 to 2025). "Notable were comparisons with IDHwt GBM (all fractions except for CD4/CD8 ratio) and with IDHmt astrocytoma (all fractions except B cells and monocytes, and CD4/CD8 ratio)." (PMID 35716311, 2022). "Given the recent observation of the abundance of CD4+ cells in canine astrocytoma, further evaluation of the source and specific role(s) of CCL2 in canine astrocytoma is warranted." (PMID 34131649, 2021). "Thus, we performed whole-cell path-clamp recording using the human astrocytoma cell line transfected with CD4 and CCR5 (cartoon) in response to gp120 application (10 ng/mL)." (PMID 40740680, 2025). "Our analyses demonstrated that there were no remarkable differences in the immune cell composition between oligodendrogliomas and astrocytomas, although the densities of some immune cells, such as CD4 memory resting cells and follicular helper T cells, showed slight differences." (PMID 34882581, 2022). "Seven out of ten markers showed a significantly different IHC expression in at least one of the evaluated cohorts whereas CD3, CD4 and 5-LOX were differentially expressed between GBMs and astrocytomas." (PMID 38816839, 2024). "In a cohort of MB, PNET, and astrocytomas, 76% of these tumors were positive for CD8+ T cells, 85% contained CD4+ T cells, and 97% contained macrophages, but these constituted only 1–10% of the total cells." (PMID 37509316, 2023). "Here, we noticed that immune cell infiltration was overall higher in astrocytoma than in oligodendroglioma, including M0, M1, and M2 macrophages, while CD8 + and CD4 + T cells were highly enriched in oligodendroglioma." (PMID 35287567, 2022). "CD3 and CD8 were positive in all detectable samples, whereas one astrocytoma sample was negative for CD4 expression." (PMID 38816839, 2024).
autoimmune encephalitis (13 papers, 2011 to 2025). Inflammation of the brain secondary to an immune response triggered by the body itself. "Our findings are in line with a previous report suggesting that Th2 differentiation and activation pathways were among the most highly represented transcriptional pathways in mice with UTX-deficient CD4+ T cells, even when exposed to a Th1/Th17 skewing experimental autoimmune encephalitis protocol." (PMID 40065718, 2025). "After depletion of CD4+ T cells in autoimmune encephalitis mice by using anti‐CD4 antibodies, the number of TRM significantly dropped, and they failed to differentiate into TCF‐1+ effector cells, thus losing the capacity for tissue destruction." (PMID 41388658, 2025). "In animal models developed for MS and autoimmune encephalitis, Th17 cells, a novel IL-17-secreting CD4+ T cell subset, have been shown to play a role in disease pathogenesis." (PMID 40806803, 2025). "Although this represents a modest proportion of Eomes + Tbet + cells, this is consistent with mouse data from experimental autoimmune encephalitis showing the capacity of Eomes + IFNγ+CD4 T cells to acquire cytotoxic attributes." (PMID 36726536, 2023). "MBP-specific CD4 T-cells isolated from spleen and liver of mice transgenic for MBP expressed in hepatocytes proliferated, and a regulatory phenotype resulted, leading to suppression of experimental autoimmune encephalitis caused by autoreactive CD4 T-cells." (PMID 21779338, 2011). "In this case, the reduced CD4/CD8 ratio could reflect the immune system’s response to the Mycoplasma pneumoniae infection and the subsequent autoimmune encephalitis." (PMID 39224609, 2024).
autoimmune gastritis (13 papers, 2009 to 2025). Inflammation of the body fundic mucosa of the stomach. "We identified four potential diagnostic markers for autoimmune gastritis by combining CD4+/CD3+ and CD8+/CD3+ ratios in the greater curvature of the antrum and those of the lesser curvature of the body." (PMID 35735608, 2022). "We further proposed an antrum CD8+/CD4+ ratio > 4.0 as a potential diagnostic marker for autoimmune gastritis." (PMID 35735608, 2022). "We propose that an antrum CD8+/CD4+ ratio > 4.0 is a potential diagnostic marker for autoimmune gastritis." (PMID 35735608, 2022). "Here we show that CD4+ T cells from H/Kα-deficient mice (H/Kα−/−) are highly pathogenic and autoimmune gastritis can be induced in sublethally irradiated wildtype mice by adoptive transfer of unfractionated CD4+ T cells from H/Kα−/− mice." (PMID 22096532, 2011). "Together, these results suggest that the development of autoimmune gastritis in mice that received CD4+ T cells from H/Kα−/− mice was caused by a T cell-mediated inflammatory response in the gastric environment rather than a more generalised response." (PMID 22096532, 2011). "In addition, we proposed antrum CD8+/CD4+ > 4.0 as a potential diagnostic marker for autoimmune gastritis, with a sensitivity of 71.4% and a specificity of 93.3%." (PMID 35735608, 2022). "To determine if adoptive transfer of T cells from H/Kα−/− mice would be able to cause autoimmune gastritis, we enriched CD4+ T cells from either H/Kα−/− or wildtype mice to ∼85% purity and transferred 5×107 of these cells into sublethally irradiated wildtype mice." (PMID 22096532, 2011). "An antrum CD8+/CD4+ ratio exceeding 4.0 exhibited a sensitivity of 71.4% and a specificity of 93.3% in diagnosing autoimmune gastritis." (PMID 37504250, 2023). "CD4+ and CD8+ T cells, along with macrophages and B cells, participate in the inflammatory process underlying autoimmune gastritis." (PMID 37504250, 2023). "CD4+ lymphocytes also play a central role in the pathogenesis of autoimmune gastritis in patients and mouse models." (PMID 35735608, 2022). "Adoptive transfer of CD4+ T cells from adult mice that had been neonatally infected with MRV to uninfected nude mice results in the development of autoimmune gastritis." (PMID 31801268, 2019). "There was a significant correlation between stomach weight and the severity of autoimmune gastritis in mice that received H/Kα−/− CD4+ T cells." (PMID 22096532, 2011). "Mice with autoimmune gastritis induced by transfer of H/Kα−/− CD4+ T cells had significantly more cells in their stomach-draining paragastric lymph nodes compared to normal mice and mice that received CD4+ T cells from wildtype donors." (PMID 22096532, 2011). "It is well documented that, in both mice and man, CD4+ T cells that recognise the gastric H+/K+ ATPase initiate autoimmune gastritis while CD8+ T cells and B cells are ineffective in doing so." (PMID 22096532, 2011). "Eight weeks after the transfer, mice that received H/Kα−/− CD4+ T cells all developed the most severe forms of autoimmune gastritis (score 5 and 6)." (PMID 22096532, 2011). "The severity of autoimmune gastritis was analysed at various time points after the transfer of H/Kα−/− CD4+ T cells." (PMID 22096532, 2011). "Autoimmune gastritis induced by the transfer of H/Kα−/− CD4+ T cells was consistently severe: all the recipient mice developed the most severe disease eight weeks after transfer and their stomach physiology was significantly affected as indicated by the increase in stomach weight and pH." (PMID 22096532, 2011). "Ectopic expression of FOXP3 in CD4+ CD25− T cells may endow CD4+ CD25− T cells with a Treg‐like suppressive capability to prevent the development of IBD and autoimmune gastritis." (PMID 33576136, 2021). "It has been previously documented that CD4+ T cells from H/Kβ−/− mice induce autoimmune gastritis in athymic BALB/c mice but not in irradiated wildtype mice." (PMID 22096532, 2011).
autoimmune gastritis (continued). "We conclude that it is the CD4+ T cells in the inoculum that caused autoimmune gastritis since it has been firmly established by many studies that CD4+ T cells and not other cell types are able to initiate autoimmune gastritis." (PMID 22096532, 2011). "Indeed, infection of CD4+CD25− T cells with a retrovirus expressing Foxp3, converted them to a regulatory phenotype, able to suppress proliferation of conventional CD4+ CD25− T cells and protect mice from autoimmune gastritis." (PMID 24350059, 2013). "Conversely, adoptive transfer of normal CD4+ T cells, but not CD8+ T cells, from uninfected syngeneic adult mice can prevent autoimmune gastritis in mice that were neonatally infected with MRV." (PMID 31801268, 2019).
Brain atrophy (13 papers, 2013 to 2025). Partial or complete wasting (loss) of brain tissue that was once present. "Several previous studies suggest that low CD4 counts might be linked to brain atrophy including cortical thinning, reductions in GM and WM volumes and ventricular enlargement." (PMID 33859326, 2021). "In conclusion, we report that dual expressing PD-1/TIM-3 CD4 and CD8 T cells are associated with neurocognitive impairment and brain atrophy, respectively." (PMID 38949728, 2024). "Recently, plasma anti-CD4 IgG levels were found to be inversely correlated with neurocognition and specific area of brain atrophy in treated HIV." (PMID 34985329, 2022). "Our recent studies identified high plasma anti-CD4 IgG levels in a cohort of PWH on suppressive ART were associated with worse cognitive performance and brain atrophy in select regions." (PMID 34985329, 2022). "Further, we show high plasma anti-CD4 IgG levels in a cohort of PWH undergoing suppressive ART were associated with worse cognitive performance and brain atrophy in select regions." (PMID 34985329, 2022). "An increased frequency of IL-21 producing CD4+ T cells had been noted in AD and the extent of brain atrophy was highly correlated with increased IL-21 producing CD4+ T cells." (PMID 35648273, 2022). "This would support the differences in the neuro-immune response observed in our TG animals and partially explain the direct correlation we found in these mice between the frequency of CD4+ T cells and the brain atrophy." (PMID 33584640, 2020). "Notably, the correlations between MRI parameters and BDNF secreting immune cells were lost in AD in whom, instead, brain atrophy was positively correlated with IL-21-producing CD4+ T cells." (PMID 24324435, 2013). "Similar to TBEV, immunopathologic mechanisms, with special regard to CD4+ and CD8+ T cells, are thought to play an important role in neuronal damage and finally brain atrophy." (PMID 34578356, 2021).
enteritis (13 papers, 2013 to 2025). Inflammation of the small intestine. "If naïve CD4+ T cells overexpress T-bet in mice with damaged immune systems, this could cause long-term enteritis regulated by Th1; in contrast, naïve CD4+ T cells with defective T-bet are incapable of inducing the disease." (PMID 30974919, 2019). "Our previous findings indicated that excessive generation of CD4+IL-10+ T cells induced by oral administration of BLS-mix to newly weaned MUC4 RR pigs with enteritis caused by an enteric pathogen might prohibit clearance of the pathogen." (PMID 27424033, 2016). "The number of CD4+CD25+Foxp3+ Tregs and CD4+IL-17A+ Th17 cells in the mesenteric lymph nodes differed significantly from the enteritis and Tregs-inhibiting groups (p<0.05)." (PMID 30364052, 2018). "The enteroendocrine I-cell derived hormone cholecystokinin is an essential mediator of initial hypophagia and is induced by CD4+ T-cells during enteritis." (PMID 23349631, 2013). "I-cell hyperplasia and CCK are essential for the initial hypophagia during enteritis, which is orchestrated by CD4+ T-cells." (PMID 23349631, 2013). "CD4+ T lymphocytes are the main effector cells when the organism suffers from enteritis." (PMID 40244038, 2025). "This study demonstrated that adoptive transfer of CD4+CD25+ Tregs can decrease mouse enteritis." (PMID 30364052, 2018). "In the liver an increased IgM and CD4 signals could be found along with enteritis." (PMID 30246797, 2018). "We have previously provided evidence that oral administration of the mCA I antigen has a suppressive effect on enteritis in Dextran sulfate sodium (DSS) model and CD4+CD25− T cell transfer model mice." (PMID 36289244, 2022). "In hyperacute enteritis induced by the anti-CD3 antibody, CD4+ T cells in the intestinal tissue at 2 h (6.753 ± 0.09838%) and 24 h (6.080 ± 0.05292%) were significantly higher than those in the control (5.337 ± 0.05783%)." (PMID 35003056, 2021). "This study suggests that the transfer of CD4+CD25+ Tregs can stabilize Foxp3 gene expression, which can influence the differentiation of Th17/Tregs, and mouse enteritis was reduced." (PMID 30364052, 2018). "There were more Foxp3+ Tregs and Smad3 and NFAT2 infiltrated into the duodenum after adoptive transfer of CD4+CD25+ Tregs, which was a significant difference relative to the enteritis group (p<0.05)." (PMID 30364052, 2018). "Mouse CD4+CD25+ Treg cells were labelled using CFSE (5,6-carboxyfluorescein diacetate succinimidyl ester) and transferred to enteritis model mice." (PMID 30364052, 2018). "In addition to morphological changes, the typical signs of enteritis, lymphocytes infiltration into both LP and IEL (intestinal epithelial layer), demonstrated by IgM and CD4 IHC signals were also found in the gut." (PMID 30246797, 2018). "Furthermore, CD4+ T-cells are identified as the key initiator in I-cell hyperplasia and resulting CCK driven hypophagia during T. spiralis induced enteritis." (PMID 23349631, 2013). "We have characterized these two phases using genetically modified mice lacking functional CCK or adaptive immunity and demonstrated that CD4+ T-cells drive I-cell hyperplasia and the resulting CCK is an essential mediator of the initial hypophagia observed during enteritis." (PMID 23349631, 2013). "Successful reconstitution was evident from CD4+ splenocytes present post-transfer and via successful worm expulsion kinetics.The adoptive transfer of CD4+ T-cells into SCID mice restored I-cell hyperplasia and initial hypophagia during T. spiralis induced enteritis." (PMID 23349631, 2013).
Glucose intolerance (13 papers, 2010 to 2025). Glucose intolerance (GI) can be defined as dysglycemia that comprises both prediabetes and diabetes. "Glucose intolerance was associated with increased lipid-associated macrophages, CD4+ and CD8+ T effector memory cells, and decreased perivascular macrophages." (PMID 37711619, 2023). "Here, we observed that short-term HFD induced dysbiosis, glucose intolerance and decreased intestinal RORγt+ CD4 T cells, including peripherally-induced Tregs and IL17-producing (Th17) T cells." (PMID 38926424, 2024). "Having demonstrated that glucose intolerance is independently associated with accumulation of IM, LAM, CD4+ TEM, and CD8+ TEM, and inversely associated with PVM (or M2-like macrophages), we next examined the transcriptome that defines these cell compartments." (PMID 37711619, 2023). "CD4+ TEM proportion and transcriptional expression were strongly associated with glucose intolerance compared with other immune cell types." (PMID 37711619, 2023). "Given the stepwise progression of CD69 expression on CD4+ T cell subsets with rising glucose intolerance, and the significant pairwise comparisons, a linear regression model was used to assess CD69 expression according to metabolic status." (PMID 30941121, 2019). "Expression of CD69 on total CD4+ T cells rose with progressive glucose intolerance (p = 0.004), which was robust to adjustment for BMI (p = 0.03 for metabolic status) and to age (p = 0.01 for metabolic status) in separate models (data not shown)." (PMID 30941121, 2019). "Glucose intolerance was highly related to CD4+ T cell gene expression pattern." (PMID 37711619, 2023). "Individuals with glucose intolerance also had greater interaction strength between cycling myofibroblast, myofibroblast, capillary endothelium, preadipocytes, progenitor cells, and, to a lesser extent, IMs and LAMs with endothelium, preadipocytes, LAMs, IMs, myofibroblasts, and CD4+ TEM cells." (PMID 37711619, 2023). "In PWH with glucose intolerance, we found higher proportion of lipid-associated macrophage (LAM) and LAM-like macrophage populations, reduction of perivascular macrophages (PVMs), and an increase in CD4+ and CD8+ T effector memory (TEM) populations that was independent of obesity, age, and sex." (PMID 37711619, 2023). "We confirmed with flow cytometry that participants with glucose intolerance had higher proportion of CD4+ CD69+ T cells (median percent: non-diabetic (6.4%), prediabetic (37.5%), diabetic (37.7%); p < 0.05 for both), which is consistent with prior studies." (PMID 37711619, 2023). "The proportions of SAT CD4+ and CD8+ memory subsets were similar across metabolic status categories in the PLWH, but CD4+ T cell expression of the CD69 early-activation and tissue residence marker, particularly on TEM cells, increased with progressive glucose intolerance." (PMID 30941121, 2019). "We previously showed that adipose tissue CD4+ T cells co-expressing CX3CR1, GPR56, and CD57 (termed ‘CGC+’ cells), a surface marker combination suggestive of antiviral activity, increased with progressive glucose intolerance and with carotid plaque burden in PWH." (PMID 36865544, 2023). "While we observed the relative proportions of SAT CD4+ and CD8+ TCM, TEM, and TEMRA cells to be similar regardless of metabolic status in PLWH, expression of CD69 on CD4+ T cells rose with progressive glucose intolerance in a step-wise progression from non-diabetic, to pre-diabetic, to diabetic." (PMID 30941121, 2019).
Immunosuppression (13 papers, 2006 to 2025). "Fourth, HIV-associated immunosuppression, measured by circulating CD4+ T-lymphocytes, negatively affects the performance of QFT-GIT, and to a lesser extent, T-SPOT.TB." (PMID 22403663, 2012). "In this cross-sectional analysis of cervical histology in HIV+/HPV+ Rwandan women we found that immunosuppression as measured by CD4 count was significantly associated with CIN3+ only in women who harbored carcinogenic HPV genotypes other than HPV16." (PMID 20976000, 2010). "Immunosuppression is a risk factor for IPD, and low CD4 T cell count is associated with poor response to pneumococcal vaccine." (PMID 34959964, 2021). "Higher percentage of female PLHIV with Immunosuppression (CD4 count value < 500) suggests that there may be gender-specific barriers to HIV diagnosis and treatment that need to be addressed." (PMID 39186499, 2024). "Immunosuppression is determined in FIV-positive cats by a progressive decline in CD4+ T cells number, reduction in the CD4+/CD8+ ratio, generalized lymphoid depletion, reduced ability to respond to antigenic stimulation and dysregulation of cytokine production." (PMID 35534884, 2022).